JAK1 (Janus kinase 1)
Diseases named in the same sentence as JAK1 in open-access papers (continued):
Sharing a sentence is not in itself a finding about the gene and the disease.
polycythemia vera (34 papers, 2015 to 2025). "Ruxolitinib, a JAK1/JAK2 inhibitor, has shown clinical benefits in polycythemia vera (PV) patients which carry an activity mutation of JAK2 gene (i.e., V617F)." (PMID 39188724, 2024). "The most notable JH2 domain genetic alterations include JAK1 V658F and the homologous JAK2 V617F mutation known to cause Polycythemia vera (PV)." (PMID 37834019, 2023). "The introduction of ruxolitinib, a JAK1/2 inhibitor, has provided an additional line of therapy, effective at controlling haematocrit, reducing spleen volume and reducing the symptom burden in polycythaemia vera (PV) and primary myelofibrosis (PMF)." (PMID 32962027, 2020). "This case report explores the consequences of ruxolitinib via inhibition janus kinase 1 (JAK1) and JAK2 pathways in the context of fungal defense in a patient diagnosed with pulmonary coccidioidomycosis during ruxolitinib therapy for polycythemia vera." (PMID 41164159, 2025). "In 2011, the first JAK1/2 inhibitor, ruxolitinib, was approved for treatment of primary and secondary myelofibrosis (COMFORT studies), and in 2014 and 2019, also for treatment of polycythemia vera (PV) and acute graft versus host disease (GvHD)." (PMID 33322351, 2020).
anemia (29 papers, 2013 to 2026). A reduction in the number of red blood cells, the amount of hemoglobin, and/or the volume of packed red blood cells. "Because JAK2 signals downstream of GM-CSF, EPO, and TPO, JAK1 selective inhibitors are expected to have a better safety profile than JAK1/JAK2 inhibitors with a lower risk of anemia." (PMID 33343569, 2020). "Filgotinib is reported to be highly JAK1-selective, causing fewer adverse events in the hematopoietic system, and may be better in the treatment of patients with iMCD with anemia and thrombocytopenia." (PMID 38927348, 2024). "This post hoc descriptive analysis of the phase 3 SIMPLIFY-2 trial evaluated the relative benefits of this approach versus switching to the JAK1/JAK2/activin A receptor type 1 inhibitor momelotinib in patients for whom anemia management is a key consideration." (PMID 38990433, 2024). "On September 15, 2023, momelotinib (JAK1/2 and ACVR1 inhibitor) received FDA approval as a treatment for patients with intermediate- or high-risk MF and anemia based on the findings of the phase 3 trials, MOMENTUM (NCT04173494) and SIMPLIFY-1 (NCT01969838)." (PMID 38201581, 2023). "Therapy with ruxolitinib, a potent JAK1/JAK2 inhibitor approved for the treatment of MF-related splenomegaly or symptoms, can be associated with dose-dependent anemia, mostly emerging in the first 12 weeks of treatment." (PMID 34017073, 2021). "Overall, the rates of anemia in upadacitinib-treated patients indicate that this drug is, at best, only relatively selective for JAK1." (PMID 35056105, 2021). "Momelotinib, apart from being an JAK1/2 inhibitor, antagonizes the effects of hepcidin; therefore, it is thought to become useful in MF with transfusion-requiring anemia." (PMID 34502471, 2021). "Momelotinib is a JAK1/2 inhibitor as well as a type 1 activin receptor (ACVR1) inhibitor being evaluated in MF patients with anemia on the premise that ACVR1 inhibition regulates hepcidin levels to restore iron homeostasis and improve anemia." (PMID 33267911, 2020). "AEs consistent with JAK1/2 inhibition are anemia, thrombocytopenia, and neutropenia, which were observed in 68%, 20%, and 32% of patients, respectively, in this study." (PMID 30105668, 2019). "Given its mechanism of action as a JAK1 and JAK2 inhibitor, the most common AEs associated with ruxolitinib were anemia and thrombocytopenia." (PMID 29804268, 2018). "As JAK2 inhibition is thought to be affiliated with the AEs of anemia seen in patients taking tofacitinib and baricitinib, likely due to JAK2′s role in erythropoiesis, it was suggested that upadacitinib’s purported JAK1-selectivity would reduce rates of anemia." (PMID 35056105, 2021). "Moreover, in a recent phase 2 trial, the JAK1/JAK2 inhibitor momelotinib has shown efficacy in the anemia of MF and a phase 3 trial comparing this drug with danazol is currently in progress." (PMID 34017073, 2021). "The recently approved luspatercept, which targets the bone morphogenetic protein-SMAD signaling pathway, and momelotinib, a newer JAK1/JAK2 inhibitor with anemia-related efficacy, have shown benefits in managing anemia in myelofibrosis." (PMID 40507313, 2025). "In the phase 3 trials of both the JAK1/JAK2 inhibitor ruxolitinib and JAK2/FLT3 inhibitor fedratinib, indicators of anemia worsening such as decreased mean hemoglobin levels and increased transfusions were evident in the initial weeks of treatment." (PMID 39682250, 2024). "Momelotinib, an inhibitor of JAK1, JAK2, and ACVR1, was approved in 2023 for the treatment of patients with myelofibrosis and anemia and has shown spleen and symptom benefits in phase 3 trials in this patient population." (PMID 38406514, 2024). "Momelotinib, a JAK1/JAK2 inhibitor with additional activity against ACVR1, is in late-stage clinical development and is hoped to address the unmet need of anemia in patients with MF." (PMID 37345196, 2023).
anemia (continued). "Momelotinib, an inhibitor of ACVR1/ALK2, JAK1 and JAK2, demonstrated activity against anemia, symptoms, and splenomegaly in the phase 3 SIMPLIFY trials." (PMID 35869266, 2022). "First clinical reports suggested a benefit of oral JAK1/2 inhibitors on CLE skin lesions, but the systemic use of these drugs is limited by side effects, e.g., anemia and thrombopenia, which mainly depend on JAK2 blockade." (PMID 32194562, 2020). "One crucial disadvantage of these drugs are their side effects, including anemia and thrombopenia, mainly depending on JAK2- and JAK3 inhibition, which prompted us to focus on JAK1 in this preclinical project." (PMID 32194562, 2020). "As expected, based on the mechanism of action of ruxolitinib as a JAK1/JAK2 inhibitor, thrombocytopenia and anemia occurred in most patients treated with ruxolitinib." (PMID 28228106, 2017). "As expected, given the mechanism of action of ruxolitinib as a JAK1/JAK2 inhibitor, the most common hematologic AEs were anemia and thrombocytopenia, but these rarely led to treatment discontinuation." (PMID 27211272, 2016). "Dual JAK1/2 and ACVR1 inhibition, such as in the case of momelotinib, provides enhanced therapeutic efficacy in MF given that the cardinal features of the disease (anemia, splenomegaly, and systemic symptoms) are concurrently treated with a single agent." (PMID 38201581, 2023). "The JAK1/JAK2 inhibitor momelotinib, currently under investigation for patients with MF and anemia, has potent inhibitory activity against ACVR1/ALK2 and may become a second-line treatment option for patients who have to eventually stop ruxolitinib due to excessive anemia." (PMID 36786879, 2023). "Anemia observed after upadacitinib treatment (selective JAK1 inhibitor) may suggest that this drug also inhibits JAK2, particularly when used in high dosage (IC50 = 0.043 μM for JAK1 vs. IC50 = 0.2 μM for JAK2)." (PMID 32796683, 2020). "However, it was less efficient in reducing stressed erythropoiesis in the PTMF model and did not correct the anaemia, as we showed for the JAK1/2 inhibitor Momelotinib 28, possibly because of its JAK2 specificity." (PMID 26176817, 2015).
Splenomegaly (29 papers, 2012 to 2026). Abnormal increased size of the spleen. "The coupled ERK1/2 and JAK1/2 inhibition efficiently reversed both fibrosis and splenomegaly even when the dosages of Ulixertinib and Ruxolitinib were reduced." (PMID 36928007, 2023). "Pacritinib is a JAK1-sparing inhibitor of JAK2/FLT3/IRAK1/activin A receptor type 1 (ACVR1) that has received accelerated FDA approval for patients with splenomegaly and/or symptoms and severe thrombocytopenia (platelet counts <50 × 109/L)." (PMID 37894394, 2023). "Ruxolitinib is a potent JAK1/JAK2 inhibitor approved for the treatment of MF-related splenomegaly or symptoms in adults with PMF, PPV-MF, or PET-MF." (PMID 34017073, 2021). "The JAK1/2 inhibitor ruxolitinib is now routinely used in patients with MF and PV for improvements of splenomegaly and disease-related symptoms." (PMID 34702814, 2021). "In the clinic, FDA-approved JAK1/2 inhibitor Ruxolitinib effectively improved the blood count and splenomegaly in myeloproliferative neoplasia (MPN) patients." (PMID 27551334, 2016). "Following approval of the first JAK1/2-inhibitor Ruxolitinib, symptoms of this inflammatory disease, characterized by splenomegaly, release of inflammatory cytokines and appearance of thrombosis, could be effectively reduced for the first time." (PMID 38967662, 2024). "Upon progressive neutrophilia and splenomegaly 5 years later, JAK1/2 inhibitor therapy with ruxolitinib was initiated resulting in a favorable clinical response and was intermittently switched to pegylated interferon alpha given the patient’s wish to father children." (PMID 35200567, 2022). "The JAK1/2 inhibitor ruxolitinib was prescribed to 12 CLL patients with abnormal serum beta‐2 microglobulin levels after 6 months or persistent lymphadenopathy or splenomegaly after 12 months on ibrutinib using a 3 + 3 phase 1 trial design (NCT02912754)." (PMID 30843659, 2019). "This review will discuss the therapies (apart from bone marrow transplant) currently used to treat splenomegaly and splenomegaly-related symptoms in patients with MF and the potential role of the JAK2 (as well as JAK1/JAK2) inhibitors." (PMID 22852872, 2012). "It inhibited the IFNγ-dependent Jak1/STAT1 signaling in LTo cells and endothelial cells within the spleen, thereby resulting in enhanced NF-κB signaling, increased proliferation of LTo and endothelial cells, and ultimately leading to splenomegaly." (PMID 39801977, 2025).
colorectal cancer (28 papers, 2011 to 2025). A primary or metastatic malignant neoplasm that affects the colon or rectum. "Further research is needed to clarify the effects of JAK1 inhibition specifically on colitis-associated colorectal cancer." (PMID 39860613, 2025). "JAK1 is an obligatory molecule subserving downstream signaling from the IFNγ receptor and JAK1 loss is well described as an immunologic escape mechanism in dMMR colorectal cancer and as a resistance mechanism to checkpoint blockade in immunogenic cancers." (PMID 37565053, 2023). "Furthermore, CPEB3 associates with tumor-related mRNAs in colorectal cancer cells, specifically targeting the 3ʹUTR of JAK1 mRNA to inhibit JAK/STAT pathways." (PMID 33146632, 2020). "In patients with colorectal cancer, JAK1 overexpression was significantly correlated with reduced survival, and the inhibition of JAK1 protein expression can impede cancer cell proliferation and progression, thereby effectively treating tumors." (PMID 40746612, 2025). "In summary, our work has demonstrated that METTL3 promoted colorectal cancer progression through upregulating JAK1 and STAT3 expression in m6A-dependent and -independent manners, contributing to the activation of the p-STAT3 signaling pathway." (PMID 38001065, 2023). "Here, we show that the 3’UTR of JAK1 is physically targeted, and JAK1 is downregulated in expression by miR-494-5p in colorectal cancer (CRC)." (PMID 38201452, 2023). "For example, the LIM protein AJUBA promotes the growth of colorectal cancer cells via suppression of the JAK1/STAT1/IFIT2 network and activates N-cadherin expression through interaction with Twist in colorectal cancer cells." (PMID 35898403, 2022). "Loss-of-function alterations, including JAK1 frameshifts, are found in less than 3% of microsatellite instability-low (MSI-L) colon adenocarcinoma samples, which make up 85% of colorectal cancer patients." (PMID 34385592, 2022). "Active JAK1 translation is induced when CPEB3 is down-regulated, causing abnormal JAK/STAT signaling activation in colorectal cancer." (PMID 33146632, 2020). "Mechanistically, CPEB3 performed as an RNA binding protein binding to 3ʹUTR of JAK1 mRNA to inhibit JAK/STAT pathways in colorectal cancer cells." (PMID 33146632, 2020). "Altogether, these results revealed that there is a mechanistic connection between CPEB3 and the JAK/STAT signal pathway, potentially via direct binding to JAK1 3’UTR in colorectal cancer cells." (PMID 33146632, 2020). "Both studies also showed that JAK1 frameshift mutations in MSI tumors are tissue specific and significantly less important in colorectal cancers as compared with endometrial cancers." (PMID 27213585, 2016). "Whether the dysregulation of the JAK1/STAT3 pathway can directly shape the characteristics of colorectal cancer cells?" (PMID 38001065, 2023). "Likewise, inhibition of JAK1 signaling induces apoptosis and cell cycle arrest and reduces tumor cell invasion in colorectal cancer cells." (PMID 37208732, 2023). "One should bear in mind, however, that mutations in JAK1 resulting in its constitutive activation have been suggested to be the initial defects in several human cancers and inhibition of JAK1 has been shown to induce apoptosis and to reduce tumour cell invasion in colorectal cancer cells." (PMID 22084725, 2011). "In colorectal cancers, PTPN2 and MET have also been recognized as modulators of JAK1/2 phosphorylation, thereby affecting the signaling of the pathway." (PMID 40909948, 2025). "LXN directly targets and inhibits JAK1, which attenuates the activity of STAT3, consistent with our previous reports on colorectal inflammation and colorectal cancer in LXN knockout mice." (PMID 39424784, 2024). "The molecular mechanism utilized by METTL3 to regulate JAK1 and STAT3 expressions has been elucidated in colorectal cancer cells, but the downstream effector that orchestrated JAK/STAT3 signaling function in cancer cells is still obscure." (PMID 38001065, 2023).
colorectal cancer (continued). "Previous studies have shown that the AJUBA protein promotes colorectal cancer cell growth by suppressing the JAK1/STAT1/IFIT2 network and activating N-cadherin expression through interaction with Twist in colorectal cancer cells." (PMID 37765273, 2023). "Thus, while it is evident that JAK1, JAK2, and B2M mutations can contribute to immune resistance in multiple types of cancer, the loss of IFNγ signaling gene expression may be the predominant source of ICB resistance in colorectal cancer." (PMID 34385592, 2022). "The comparison of clinical variable-associated mutation genes between the two ethnic groups showed little overlap, and only a few key colorectal cancer genes such as APC and JAK1 were common." (PMID 35003350, 2021). "In previous reports, inhibition of JAK1 and 2/STAT3 signaling was reported to induce apoptosis and cell cycle arrest in colorectal cancer cells." (PMID 34721022, 2021). "On the contrary, research into the IFN-γ/JAK/STAT1/IFIT2 pro-apoptotic pathway has uncovered that AJUBA, with increased expression in colorectal cancers, may induce tumor progression by specifically binding to the FERM domain of JAK1." (PMID 40909948, 2025). "Collectively, our results revealed that METTL3 simultaneously upregulated JAK1 and STAT3 expression in m6A-dependent and -independent manners, which contributed to STAT3 signaling activation, resulting in colorectal cancer proliferation and progression in vitro and in vivo." (PMID 38001065, 2023). "Besides, inhibition of JAK1,2/STAT3 signaling induces apoptosis, cell cycle arrest, reduces tumor cell invasion in colorectal cancer cells." (PMID 26474284, 2015). "In colorectal cancer cell lines such as HT-29 cells, IFN-γ + TNF-α-induced cell death is driven by the JAK1/2-STAT1 pathway and supported by the non-enzymatic scaffold function of caspase-8." (PMID 39860613, 2025).
psoriatic arthritis (25 papers, 2019 to 2025). Joint inflammation associated with psoriasis. "Approved by the FDA, EMA, and other regulatory agencies, upadacitinib (Rinvoq) treats chronic inflammatory diseases such as RA, psoriatic arthritis, and ulcerative colitis by inhibiting JAK1, disrupting cytokine signaling." (PMID 40283434, 2025). "Filgotinib, a Jak1 inhibitor, and upadacitinib, a Jak1 inhibitor with partial selectivity for Jak2, have also been approved for the treatment of psoriatic arthritis." (PMID 36834806, 2023). "The selective JAK1 inhibitor Upadacitinib is currently being investigated as an alternative to tofacitinib for treating RA and psoriatic arthritis, but it may also be interesting for the treatment of type 2 immune diseases since IL-4Rα also uses JAK1 for signaling." (PMID 31708926, 2019). "Tofacitinib, an inhibitor of JAK1/3, has been approved by the US FDA for psoriatic arthritis and shows promise for treating plaque psoriasis." (PMID 39201060, 2024). "Tofacitinib, a JAK1/JAK3 inhibitor, has been approved for RA and psoriatic arthritis, whereas baricitinib is a JAK1/JAK2 inhibitor approved for RA and the treatment of AD in Europe." (PMID 35269828, 2022). "Tofacitinib has been FDA-approved for psoriatic arthritis (PsA), whereas baricitinib (the JAK1 and JAK2 inhibitor) and upadacitinib (the selective JAK1 inhibitor) have been FDA-approved for RA." (PMID 32432116, 2020). "Tofacitinib inhibits JAK1 and JAK3 and is approved for the treatment of RA and psoriatic arthritis." (PMID 31708926, 2019).